SCD (stearoyl-CoA desaturase)
Diseases named in the same sentence as SCD in open-access papers (continued):
Sharing a sentence is not in itself a finding about the gene and the disease.
tumor (continued). "Conversely, SCD1 knockdown MC38 by shRNA showed reduced tumor growth, although not significant possibly due to the redundant expression of SCD isoforms SCD2-4." (PMID 35793868, 2022). "Although the growth rate of the CRClow SCD cells was slightly decreased in vitro, knockdown of SCD expression did not have any noticeable effect on tumor growth in vivo." (PMID 35342344, 2022). "Lipid metabolites of stearoyl-CoA-desaturase (SCD) activity are abundant in aggressive HCC samples and could promote tumor invasion and tumor incidence, and MUFAs are more abundant in CSCs than in their non-stem counterparts." (PMID 35721518, 2022). "Although SCD plays a role in inflammatory diseases, no direct evidence has revealed its relationship with tumor immunity." (PMID 34742349, 2021). "However, in SCD inhibitor–treated mice, where late-stage tumors overexpress SCD, and presumably acquire resistance in vivo through FOSB overdrive, FOSB shRNA slowed tumor growth and improved survival of mice." (PMID 33568479, 2021). "Together, these results demonstrate that the SCD inhibitor CAY10566 penetrates the BBB, hits the target, reduces tumor burden, blocks hemorrhage, extends survival of mice with intracranial GBM as a single agent, and improves survival in combination with TMZ relative to TMZ alone." (PMID 33568479, 2021). "In clear contrast, the genes involved in FA desaturation (stearoyl-CoA desaturase, SCD5) and PUFA trafficking (fatty acid-binding protein 7, FABP7; acyl-CoA synthetase 4, ACSL4; phospholipase A2G2D, PLA2G2D) were upregulated in tumours with PI(18:0/20:3) accumulation." (PMID 31819188, 2020). "Therefore, the aim of this study was to analyze the mRNA expression of desaturase genes—SCD, SCD5, FADS1, FADS2, and FADS3—in GBM in three tumor zones: necrotic core, growing tumor area, and peritumoral area." (PMID 32392704, 2020). "Similarly, the SCD-1 inhibitor, CAY10566, inhibits glioblastoma stem cells expansion and in vivo tumor growth." (PMID 32486505, 2020). "We next analysed the relationship between SCD/PI3 levels and tumour progression status." (PMID 30592142, 2019). "Cisplatin can augment anti-tumor immune responses in combination with immune checkpoint blockers (such as PD-1/PD-L1 or CTLA4 inhibitors), lipid metabolism disruptors (like FASN inhibitors and SCD inhibitors) and nanoparticles (NPs), resulting in better outcomes." (PMID 39757995, 2025). "Moreover, the tumor immune estimation resource and TISCH databases showed a significant positive correlation between the expression of SCD and the abundance of CD8+ T cells and macrophage cell infiltration, while the expression of FADS2 was positively correlated with the abundance of B cells." (PMID 38905386, 2024). "Hence, the ability of DENSPM to simultaneously suppress FASN, SCD, and FADS2 could be of critical importance for successful tumor treatment." (PMID 39337514, 2024). "Therefore, it should not be concluded that SCD expression enhances the anti-tumor effects of immune cells." (PMID 39351232, 2024). "Tumor cells undergo lipid metabolic reprogramming through de novo lipogenesis involving key transcription factors such as sterol regulatory element binding protein (SREBP), ATP citrate lyase (ACLY), acetyl-CoA carboxylase (ACC), fatty acid synthase (FASN) and stearoyl-CoA desaturase 1 (SCD1)." (PMID 38189049, 2023). "However, the increased SCD-1 expression observed in Dox-H compared to Dox-L mice in tumor tissue does not account for the decreased MUFAs found in the tumor tissue of Dox-H mice." (PMID 32257945, 2020). "The blockage of key lipid metabolic enzymes such as ACLY, FASN, ACACA, and stearoyl CoA desaturase (SCD), as well as the upstream regulator sterol regulatory element-binding proteins (SREBPs) in various neoplastic cells could suppress tumor cell malignancy both in vitro and in vivo." (PMID 31416244, 2019).
tumor (continued). "Significantly downregulated genes in NHT tumours (DESeq comparison; Benjamini-Hochberg P <0.05) were typically androgen responsive (for example, TMPRSS2, KLK3, BMPR1B, TPD52) or steroidogenesis-related (for example, DHCR24, SCD), consistent with a reduction in androgen receptor activity." (PMID 25155515, 2014). "The results could be confirmed in an ex vivo mouse model, where tumours from implanted cells grew in the tissue context of precision-cut lung slices, and only for wild-type Zeb1, but not for Zeb1-depleted cells, SCD inhibition cooperated with ML210 to reduce tumour growth by ferroptosis." (PMID 39009641, 2024). "Interestingly, SCD2 expression could not completely rescue stearoyl-CoA desaturase activity in the SCD1 null tumor cells, as these tumors demonstrated significantly decreased MUFA content in their TG and CE lipid pools." (PMID 24069385, 2013). "Specifically, the NR3C2, ANPEP, and FCGRT genes were significantly upregulated in tumor tissues, while PIK3R1, MME, SCD, and SERPINE1 genes were notably downregulated." (PMID 41011246, 2025).
metabolic disorders (69 papers, 2008 to 2026). "The over-expression of SCD has been linked to various metabolic diseases, highlighting its potential as a therapeutic target." (PMID 39966220, 2025). "Therefore, the balance of SCD activity is crucial to health, and its deficiency induces metabolic disease, including adiposity decrease, lipid oxidation, and insulin sensitivity increase." (PMID 39327557, 2024). "The overexpression of SCD is associated with metabolic disorders and may lead to pathological changes in the liver as one of the adaptive mechanisms." (PMID 34445384, 2021). "Studies on human adipose tissue revealed that visceral adipose tissue (in excess, leading to serious metabolic disorders) was characterised by a higher SCD and EVOLV6 ratio than subcutaneous adipose tissue." (PMID 41002979, 2025). "SCD is an important metabolic control factor; inhibition of its expression enhances the therapeutic effects on many metabolic diseases." (PMID 32016349, 2020). "It is also possible that inflammation could be enhanced by a metabolic disorder associated with elevated POA level and SCD-1 activity." (PMID 30258503, 2018). "An SCD-1 inhibitor that reduces SCD-1 activity may serve as a therapeuticstrategy for metabolic disorders, but very few reports are available for the useof SCD-1 inhibitor." (PMID 18566691, 2008). "PPARγ participates in mediating metabolic disorder via numerous downstream adipogenic and lipogenic genes, which are important for adipocyte maturation, lipid accumulation, and insulin-sensitive glucose transport, including FAS, ACC, aP2, SCD-1, and CD36." (PMID 23533476, 2013).
infection (29 papers, 2009 to 2025). The state of being infected such as from the introduction of a foreign agent such as serum, vaccine, antigenic substance or organism. "Nevertheless, SCD was detected in every examined cell line, displaying a successful infection and functional transcription of the encoded gene, thus making it possible to exploit its suicide function in the following experiments." (PMID 38339240, 2024). "SCD is one of the key enzymes in the melanin biosynthesis pathway, and the expression of this gene will affect the infection efficiency of C. gloeosporioides." (PMID 32547526, 2020). "Conversely, reintroduction of SREBP1c in HCT116 by infection with an adenovirus restored SCD expression in nutlin-3 treated cells and reversed the phospholipid profiles." (PMID 26061814, 2015). "It was interesting to note that the infection was almost completely resolved from liver and spleen of animals treated with SCD-1." (PMID 25140804, 2014). "The in vivo efficacy of SCD-1 against A. fumigatus-induced infection was studied in female swiss albino mice." (PMID 25140804, 2014). "AGO4, SNX9, SCD were also downregulated after infection with MA08." (PMID 34671358, 2021). "Of note, SCD was previously reported to be marginally but consistently upregulated during DENV-2 infection in HEK293 T cells, but first up- and then downregulated after infection in HepG2 cells, similar to what we observed in Huh7 cells." (PMID 39863099, 2025). "As the infection progressed, FADS2 as well as SCD mRNAs were both significantly reduced (48 hpi)." (PMID 39863099, 2025). "qRT-PCR analysis showed that DHCR7, SCD, and HMGCR mRNA levels were significantly increased in moDCs infected with ZIKV-EGFP-BeH819015 or ZIKV PRVABC59 compared with Mock and ZIKV− moDCs, as was observed following infection with ZIKV SD001." (PMID 36097162, 2022).
cardiovascular disease (16 papers, 2013 to 2025). "MUFA levels, which are products of SCD, are positively associated with the development of cardiovascular disorders." (PMID 36982607, 2023). "This review discusses the role of stearoyl-CoA desaturase 1 in the regulation of cardiovascular homeostasis and the development of heart disease and presents markers of systemic stearoyl-CoA desaturase activity and their predictive potential in the diagnosis of cardiovascular disorders." (PMID 36982607, 2023). "In previous studies, dietary and circulating fatty acids (FA) and desaturases activity (delta-5 desaturase [D5D], delta-6 desaturase [D6D], and stearoyl-CoA desaturase [SCD-16]) involved in their metabolism were associated with metabolic and cardiovascular disorders." (PMID 32486144, 2020).
adenocarcinoma (4 papers, 2019 to 2022). A common cancer characterized by the presence of malignant glandular cells. "Moreover, SCD can be directly inhibited with the small molecule MF-438 which sensitized adenocarcinoma cells to cisplatin treatment." (PMID 30785874, 2019).
neurodegenerative disease (4 papers, 2022 to 2024). A disorder of the central nervous system characterized by gradual and progressive loss of neural tissue and neurologic function. "New tools for localizing, identifying and quantifying lipids and the genes that regulate them have highlighted the importance of the SCD-regulated balance between saturated and unsaturated fatty acids in aging and neurodegenerative diseases." (PMID 35443751, 2022). "Interestingly, dysregulation in levels of monounsaturated fatty acids (MUFA) have emerged in studies of AD and other neurodegenerative diseases, with remarkably beneficial effects found by lowering activity of Stearoyl-CoA desaturase (SCD), the rate limiting enzyme in MUFA synthesis." (PMID 38565895, 2024). "Numerous evidence also indicated that PARP1, SCD, AR, ALOX5, HIF1A are critical involved in HD or neurodegenerative diseases." (PMID 38918688, 2024).
skin disorder (3 papers, 2020 to 2024). Any deviation from the normal structure or function of the skin or subcutaneous tissue that is manifested by a characteristic set of symptoms and signs. "Sebaceous gland atrophy and other skin disorders have been reported in SCD knockout mice and also after SCD1 inhibition by A-939572 administration, possibly mediated through blockade of the androgen-induced transcription of SCD1 gene." (PMID 31936134, 2020).
heart disease (2 papers, 2019 to 2023). "In this chapter, we will focus on the role of SCD1 in the pathogenesis of heart disease, the role of SCD1 in regulating cardiac metabolism, and the manipulation of SCD activity as a promising therapeutic intervention in lipotoxic cardiomyopathy." (PMID 36982607, 2023).
infectious disease (1 paper, 2021). A disorder directly resulting from the presence and activity of a microbial, viral, or parasitic agent in humans. "Both resistin (RETN) and stearoyl-CoA desaturase (SCD) are molecules that regulate lipid metabolism, and there are few studies on them in infectious diseases." (PMID 35059324, 2021).
reproductive system tumors (1 paper, 2024). "Interestingly, there was a significant difference in the survival curve of patients with high and low SCD expression in reproductive system tumors (BLCA, CESC, KICH) and intracranial tumors LGG." (PMID 38625951, 2024).
SCD also shares sentences with these, for which no sentence is quoted: renal cell carcinoma (9 papers); liver (8); acne (5); esophageal squamous cell carcinoma (5); chronic myeloid leukemia (4); colorectal adenocarcinoma (4); endometrial cancer (4); gastric tumor (4); lymphoma (4); pulmonary fibrosis (4); autoimmune disease (3); coronary artery disease (3); demyelinating disorders (3); hypothyroidism (3); metastatic tumors (3); neurological disorders (3); alcoholic fatty liver disease (2); Anxiety (2); autoimmune disorders (2); bacterial infection (2); Barrett esophagus (2); Cachexia (2); chronic kidney disease (2); colon adenocarcinoma (2); colorectal tumor (2); cutaneous melanoma (2); endometriosis (2); fibrosis (2); intestinal diseases (2); kidney cancer (2).
A further 130 diseases each share a sentence with SCD in 2 papers or fewer.